SOX2 (SRY-box transcription factor 2)
Diseases named in the same sentence as SOX2 in open-access papers (continued):
Sharing a sentence is not in itself a finding about the gene and the disease.
tumor (continued). "Here, we investigated the epigenetic regulation of pluripotency-associated genes NANOG, OCT4, c-MYC, KLF4, and SOX2, and their correlation with gene expression in cancer cell lines and primary tumor samples." (PMID 24023739, 2013). "One of the analyzed samples showed loss of SOX2 amplification in metastatic versus primary tumor tissue." (PMID 23544055, 2013). "In conclusion, we have identified >280 proteins that associate with SOX2 in DAOY MB tumor cells and demonstrate that two of the SOX2-associated proteins, MSI2 and USP9X, play key roles in the growth of MB and GB cells." (PMID 23667531, 2013). "Among them, CSCs displaying an embryonic stem cell ‘stemness' signature, based on the expression of Oct-4, Nanog and Sox2, are present in distinct high-grade tumor types associated with poor prognosis." (PMID 23828569, 2013). "The data presented here strongly suggest an important autocrine/paracrine function of the cluster cells as signalling centres within the tumour and the interplay with the stromal cells, which is maintained after loss of SOX2 expression." (PMID 22349813, 2012). "Notably, SOX2 levels are inversely associated with tumor grade and positively associated with progression-free survival." (PMID 41268614, 2026). "For example, in NSCLC patients with non-adenocarcinoma subtypes, the expression of transglutaminase 2 is linked to tumor recurrence and disease-free survival, and SOX2 is hypothesized to regulate this." (PMID 41268614, 2026). "It is possible that the stemness-associated transcription factor Sox2, which is required for tumor formation by this route, itself plays a role in the transition to malignancy, however it is also possible that Sox2 is simply required for LNM cell growth or survival." (PMID 40571713, 2025). "For confirmation, MSC-associated protein levels of CD74 and SOX2 in tumor tissues were examined." (PMID 39940960, 2025). "Consistent with the genomic categories, cases with a high tumor mutation burden (TMB) above 10 mutations/Mb had a higher prevalence in the group with suppressed SOX2 mRNA, while CIN metrics AS and FGA were more often high in the group with retained SOX2 expression." (PMID 40149431, 2025). "RNA-seq studies were performed to examine the effect of Sox2 loss on tumor cells." (PMID 40128799, 2025). "Indeed, the enhanced glial progenitor-like profiles including Rspo1, Zfp423, and Msx1 were significantly reduced, whereas Otx2 mRNA levels remained unaltered in Sox2-deficient tumor cells." (PMID 40128799, 2025). "In addition, elevated levels of stem cell-related proteins such as NANOG, Oct-4 and Sox2 have been implicated in increased tumour aggressiveness and metastasis." (PMID 39316249, 2025). "Immunofluorescence of brain tissue revealed extensive localization of DiD-labeled R-EVs, accompanied by increased expression of stem cell markers (SOX2, Nestin) and the Ki67 proliferation marker in the tumor region and associated statistics indicated the Ki67, SOX2 and Nestin area to DAPI (%)." (PMID 40093910, 2025). "Furthermore, patients with primary OSCC showing a high SOX2 expression are associated with a younger age, lower tumor size, lower clinical stage, and a lower incidence of extracapsular spread." (PMID 39180200, 2025). "An additional twist is that in lung, head and neck, esophageal, and cervical SCCs, the 3q chromosomal region is often amplified, and this region contains not only TP63 but also SOX2, which encodes another transcription factor widely involved in tumor progression among SCCs from different body sites." (PMID 39455281, 2025). "In addition to promoting EMT, SOX2 has been implicated in therapeutic resistance and tumor plasticity, further enhancing tumor invasiveness." (PMID 40735045, 2025). "In addition, we found that three cancer cell stemness‐associated markers, Bmi1, CD133, and Sox2, were also expressed in the majority of B7‐H3 positive tumor cells in primary CRC samples from 48 patients." (PMID 40859957, 2025).
tumor (continued). "Furthermore, aberrant expression levels of SOX2 are associated with heightened invasive and metastatic capabilities in these tumor cells." (PMID 39976818, 2025). "Their expression was upregulated in NOTCH-driven CPP, but decreased in Sox2-deficient tumor cells." (PMID 40128799, 2025). "Indeed, the subgroup of tumors with high SOX2 but low SOX9 expression (SOX2highSOX9low) was significantly associated with a smaller tumor size (p < 0.042) and lower probability for lymph node metastasis (p < 0.026)." (PMID 39180200, 2025). "Using the Open Targets database, we confirmed that SOX2 is predominantly associated with neoplasms." (PMID 41388088, 2025). "Overall, these data demonstrate that SOX2 loss promotes tumor growth in A253-derived SG-SCCs." (PMID 38951654, 2024). "SOX2 is strongly associated with the genesis and progression of various tumours." (PMID 38494478, 2024). "In AAC, SOX2 expression was linked to large tumor size and short patient survival." (PMID 38532463, 2024). "In addition, numerous studies have supported the assumption that SOX2 expression is associated with a tumor-initiation capacity." (PMID 38275880, 2024). "Thus, Notch signaling and SOX2 seem to be implicated in a Yin and Yang relationship promoting distinct tumor cell states." (PMID 39478150, 2024). "SOX2 has been implicated in various aspects of tumor initiation and maintenance." (PMID 38398118, 2024). "In addition, they strongly upregulated the NSC markers Sox2, Nes, and Ptprz1, indicative of a more stem/progenitor-like state associated with tumor aggressiveness." (PMID 39285246, 2024). "For instance, the transcription factor SOX2 may play a regulatory role in tumor immunity, particularly in association with T cell immunity." (PMID 39286028, 2024). "SOX2 expression is associated with tumor progression and prognosis." (PMID 38607066, 2024). "Among them, ERG, ZFX and SOX2 have been reported to be highly associated with tumor development." (PMID 38389573, 2024). "SOX2 has also been implicated as essential for OS tumour growth and cell proliferation." (PMID 38689429, 2024). "Subgroup analysis was conducted to evaluate the association of c-MET and SOX2 with the tumor stage, which showed that the odds of early-stage presentation in SOX2 immuno-positive cases are 75% lower compared to immuno-negative cases (OR = 0.25; 95% CI 0.14–0.45, p < 0.00001, I2 = 0%)." (PMID 37109090, 2023). "In effect, SOX2 has previously been linked to tumor aggressiveness." (PMID 36932385, 2023). "The loss of expression of Sox2 significantly reduces the ability of tumor cells to grow and expand." (PMID 37888115, 2023). "The upregulation of OCT3/4 and SOX2 could therefore be correlated with the increased risk of malignant transformation and the worse tumor prognosis." (PMID 37859926, 2023). "Further immunophenotyping studies using spheroid sections may be helpful in matching CAF and CIC identification with the expression of markers such as NANOG and SOX2, considering their confluent association with tumor prognosis." (PMID 37830632, 2023). "Similarly, they induced the upregulation of HIF-1α, VEGFα, and SOX2 genes associated with tumor vascularization and tumor cell proliferation, migration, and invasion." (PMID 38013688, 2023). "Previous data suggest that dormant disseminated tumor cells not only undergo a deep growth arrest but also exhibit an upregulation of genes associated with self-renewal and pluripotency, including Sox9, Oct4, Sox2, and Nanog." (PMID 37958610, 2023). "In view of the hypothesis that the presence of stem cells within GBM may be related to chemoresistance and a quiescent phenotype within the tumor, we determined whether SOX2- or CD133-expression was associated with clinical outcome." (PMID 36333778, 2022). "In cSCC, ectopically-expressed Sox2 is implicated in tumor initiation and malignant progression." (PMID 35892887, 2022).
tumor (continued). "Since Nestin, CD44 and SOX2 are associated with stemness in GB, their elevated levels in the GB tumor samples suggested that these markers may drive the progression and radioresistance of GB." (PMID 35269397, 2022). "Consistent with this, lactate supplementation also increased in the A549 and H358 cell lines the proportion of the subpopulations characterized by elevated GLDC, Aldehyde dehydrogenase (ALDH) activity and SOX2 expression, critical markers associated with heightened tumor initiation capacity." (PMID 35877003, 2022). "Of note, the immune landscape of tumor specimens showed that the SOX2 expression is positively associated with the regulatory T cell (Treg) infiltration and is negatively related to M1-like macrophages, which is consistent with the fact that IFNI promotes M1-like polarization of APCs." (PMID 35267473, 2022). "We show that this signaling axis is operative across different types of human cancer and may affect additional tumor contexts given that SOX2 is expressed and implicated in at least 20 types of human cancer and MYC is deregulated in up to 70% of cancers." (PMID 35454854, 2022). "Sox2+ cells were susceptible to develop tumours in a mouse model with a mutation in Apc." (PMID 35269931, 2022). "Moreover, Bcl-2 was upregulated along with SOX2 and associated with high-grade tumor as well as advanced-stage of HCC." (PMID 34436030, 2021). "Additionally, a recent report states that VDR restricts stemness and chemotherapy resistance by regulating SOX2, a factor that maintains tumor-initiating cells, and is associated with poor prognosis." (PMID 34867333, 2021). "Given the strong association of SOX2 with spheroid formation and tumor initiation, we evaluated whether knockdown of SOX2 enhanced the sensitivity of HGSOC lines to carboplatin." (PMID 33445692, 2021). "Loss of SOX2 also reduced the growth rate of tumor xenografts." (PMID 33952719, 2021). "Combining Sox2 overexpression with tumour suppressive Pten and Cdkn2a mutations leads to LUSC-like tumours regardless of whether the Cre-driver gene is expressed by basal, club or AT2 cells." (PMID 33435818, 2021). "Besides, SOX2 was reported to be associated with early tumor initiation, and its level in high-grade serous carcinoma (HGSC) effusions was demonstrated to be markers of clinically aggressive disease." (PMID 34621737, 2021). "However, cellular reliance on p63 and SOX2 seems to diminish as the tumor grows, and increasing evidence suggests the loss of these proteins is correlated with tumor metastasis." (PMID 33799513, 2021). "It is likely that aberrant activation of SOX2 promoter upon epigenetic changes within tumor microenvironment could cause a subpopulation of tumor cells to shift towards a cancer stem-like phenotype." (PMID 30517668, 2020). "Association of 3q26 amplification with PKCi–SOX2–HHAT signaling axis might also play a regulatory role by imparting stem-like phenotypes in different tumor types harboring these chromosomal alterations." (PMID 30517668, 2020). "To begin to address this deficiency, we examined whether elevation of SOX2 in five different tumor cell lines alters the fraction of cells in the G1, S, and G2/M phases of the cell cycle." (PMID 32998722, 2020). "Higher levels of SOX2 protein expression (10%–60%) in SOC was associated with tumor aggressiveness in terms of histopathological and clinical manifestations, indicating that SOX2 might have played a pivotal role in maintenance of stem-like features of SOC." (PMID 30517668, 2020). "Thus, elevating SOX2 in tumor cells appears to cause growth inhibition independently of the prognostic significance of SOX2." (PMID 32998722, 2020). "In particular, we decided to test ALDH and SOX2 in our PSP samples for the well-known vascular aspect of this tumor which may be associated with the role that these two markers have into the tumor vascularization process." (PMID 32984377, 2020).
tumor (continued). "Besides, we found a moderate correlation between the proportion of Sox2+ cells and tumour take in mice, pinpointing an association between Sox2 expression and tumourigenicity of transplants." (PMID 32260145, 2020). "In Apc-deficient PSCC, Sox2 may collaborate with β-catenin to regulate the pro-tumor transcriptome, such as upregulation of cyclin D1 in breast cancer." (PMID 32358507, 2020). "In addition, Met-1 tumor cells from obese mice expressed significantly higher expression of CSC-associated genes Sox2 and Notch Receptor 2 (Notch2), as well as Notch ligand Dll1 and downstream regulator Dtx2." (PMID 32098183, 2020). "Together, we concluded that SOX2 prompted tumor progression through causing CD8+ T-cell tolerance." (PMID 33158915, 2020). "Sox2 associated with USP9X regulates the growth of tumor cells in the brain." (PMID 33158118, 2020). "Finally, Sox2 has tumor-specific associations with patient outcomes similar to TrkB: negative in LASC, mixed for head and neck SCC overall, and positive in LUSC." (PMID 31221127, 2019). "In this study, a high expression of SOX2 was associated with early stage of the tumor (p=0.029)." (PMID 31508790, 2019). "SOX2 has been already associated with tumor initiation, growth, drug resistance, and metastasis." (PMID 30466459, 2018). "Moreover, the loss of SOX2 was predominantly observed in solid ACCs as well as advanced tumor stages." (PMID 29596469, 2018). "Thus, Wibertz and coworkers have studied two cohorts of LSQCCs, for a total of 891 patients and have observed that 8% of these patients display a high level of SOX2 amplification, associated with lower tumor grade and a prolonged overall survival." (PMID 30060526, 2018). "The results based on the database also supported the hypothesis that Sox2 expression is associated with a poor prognosis at earlier tumor stages." (PMID 28046028, 2017). "In addition, a meta-analysis found that SOX2 expression was associated with tumor size, histological grade, the aggressiveness and lymph node metastasis in TNBC patients." (PMID 29527291, 2017). "Expression of degradation-resistant β-catenin in Sox2+ cells leads to the formation of β-catenin-accumulating cell clusters that resemble those in human aCP, implicating Sox2+ progenitor cells as the cells in which the tumour-initiating mutation in β-catenin occurs." (PMID 28781761, 2017). "In addition to survival and recurrence, in the majority of cancers examined thus far, high SOX2 expression has been linked to the infiltrative and metastatic capacity of tumor cells." (PMID 28388544, 2017). "Interestingly, proteomic analysis of the SOX2-interactome indicates that SOX2 associates with several DUBs that exert important roles in tumor cells, including USP9X, USP7, USP15, USP24, and USP34." (PMID 28388544, 2017). "In this tumor, SOX2 can associate with the gene regulatory regions of miR145, where it is believed to repress miR145 transcription; whereas miR145 reduces the expression of SOX2 by interfering with its translation." (PMID 28388544, 2017). "Previous studies have shown that CD133 and Sox2 are exclusively expressed at perinecrotic and perivascular regions associated with stem-like cell pools, and that nestin and Musashi-1 are homogeneously expressed across the tumor, identifying precursors." (PMID 28412969, 2017). "Its focal expression, instead, shapes NED in PC and confers selected clones with invasive and migratory properties, as corroborated by gene transfection, by functional studies and by the finding of a strong association between SOX2 mRNA expression in the primary tumor and lymph node metastasis." (PMID 26540632, 2016).
tumor (continued). "These spheroids, that represent a validated and widely used method to study cancer stem cells in vitro, are enriched in cells with stem-like phenotype, expressing CD133, ABCG-2, Oct-4, Sox-2 that are directly associated with stemness features and tumor formation in vivo." (PMID 27367907, 2016). "In addition, SOX2 was identified as a regulatory factor in several key signaling pathways associated with tumor progression, including the Akt, Wnt and MAPK pathways." (PMID 26969300, 2016). "Importantly, high levels of SOX2 have been associated with tumor aggressiveness and worse prognosis." (PMID 27822457, 2016). "SOX2 has a crucial role in maintaining the stem cell-like phenotype in cancer cells and its overexpression is generally associated with aggressive disease and poor outcome in several different tumor types." (PMID 26780934, 2016). "Considering the redundancy of signaling factors in tumor cells, other members of the same protein family or different pathways may compensate for the loss of Sox2 leading to the survival of tumor cells." (PMID 27371094, 2016). "Indeed, the expression of EGFRvIII positively correlates with the expression of SOX2 and is associated with an enhanced self-renewal ability and tumor-initiating activity." (PMID 27822457, 2016). "Importantly, this study demonstrated that SOX2 expression is closely associated with putative cancer stem cell markers previously reported to be expressed by PDAC tumor-initiating cells." (PMID 27145457, 2016). "Recent study suggested the enrichment of SOX2 expression in tumor spheres may be due to loss of the SOX2 repressing miRNAs27." (PMID 25897700, 2015). "Consistently, we found that the three main genes belonging to the stem cell regulatory network (POU5f, which encodes Oct4, NANOG and SOX2) were all significantly overexpressed in LMNA-KD-derived tumor spheres and even more so when the sphere cell population was cultured as adherent cells." (PMID 26439802, 2015). "We also noticed that SOX2 expression was significantly associated with pathological tumor stage of TCC, which indicated that SOX2 expression may be associated with progression in TCC." (PMID 28983346, 2015). "Since SOX2 is a target of amplification in different tumors, we hypothesized that this genetic alteration, frequently associated with tumor progression, could explain not only the expression but also the heterogeneity of SOX2." (PMID 25300947, 2014). "Together, these findings suggest that SOX2 in part through upregulation of FGFR1 might enhance distant spreading of tumor cells to the liver, thereby causing a poorer patient survival." (PMID 25010701, 2014). "The aim of this study was to determine whether such responses reflect a particular pattern of SOX2 protein expression in the tumor and whether this pattern associates with clinical outcome." (PMID 24940116, 2014). "Conversely, reduction of Notch signaling is associated with reduced proliferation, increased apoptotic susceptibility, reduced tumor-sphere formation, prevention of in vivo tumor implantation, and changes in the expression of stemness transcription factors [Oct-4, SOX2, Nanog; Ref." (PMID 24550888, 2014). "In particular, we demonstrated in our cohort that SOX2 expression correlated with a higher risk of tumor recurrence (p=0.017) and with a shorter disease-free survival compared to SOX2 tumors (median: 34.9 months; 95% CI: 7.5-62.2 vs. median: 60.3 months; 95% CI: 32.6-88.1, respectively)." (PMID 25127259, 2014). "However, despite its oncogenic potential in numerous tumour types, the suppression of SOX2 has been reported as a hallmark of gastric carcinoma." (PMID 25156079, 2014). "Interestingly, in spite of induction of partial differentiation, supported by loss of OCT3/4, all tumor cells remained positive for SOX2." (PMID 24404135, 2014).